OR52L1 (olfactory receptor family 52 subfamily L member 1)
Description:
Odorant receptor.
Synonyms: OR11-50
Tractability: Antibody: UniProt places it where antibodies can reach, with medium confidence; UniProt predicts a signal peptide or a membrane-spanning region; its Gene Ontology location is reachable by antibodies, with medium confidence.
Gene: Protein-coding gene on chromosome 11 (5,985,892 to 5,986,985, reverse strand). Ensembl gene ENSG00000183313.
Subcellular location: Cell membrane
Pathways (Reactome):
Sensory Perception: Expression and translocation of olfactory receptors
Gene Ontology:
Molecular function: protein binding; olfactory receptor activity; G protein-coupled receptor activity
Biological process: detection of chemical stimulus involved in sensory perception of smell; G protein-coupled receptor signaling pathway; nervous system process
Cellular component: plasma membrane; membrane
Genetic constraint (gnomAD): Loss-of-function variants: 15 observed, 17.17 expected, observed/expected ratio (o/e) 0.87, 90% interval 0.58 to 1.35. The upper end of that interval is the gene's LOEUF score, 1.35, which puts it in group 5 of 6, group 1 being the genes least tolerant of losing a copy. Missense variants: 406 observed, 414.85 expected, observed/expected ratio (o/e) 0.98, 90% interval 0.9 to 1.06. Synonymous variants: 166 observed, 166.7 expected, observed/expected ratio (o/e) 1, 90% interval 0.88 to 1.13.
Homologues: Orthologues: chimpanzee OR52L1 (97% identical), rat Or52l1b (85% identical), guinea pig OR52L1 (84% identical), macaque OR52L1 (84% identical), rat Or52l1 (83% identical), dog OR52L1 (82% identical), mouse Or52l1 (82% identical), dog OR52L2 (81% identical), tropical clawed frog or52m1 (46% identical). Paralogues in human: OR52R1 (55% identical), OR52D1 (50% identical), OR52K1 (50% identical), OR52K2 (50% identical), OR52M1 (49% identical), OR52N4 (49% identical), OR52W1 (48% identical), OR52E8 (48% identical), OR52J3 (47% identical), OR51E2 (47% identical), OR52A5 (47% identical), OR52E2 (47% identical), and 39 more.
Diseases named in the same sentence as OR52L1 in open-access papers:
OR52L1 is named in the same sentence as 2 diseases in open-access papers, as found by Europe PMC text mining. Sharing a sentence is not in itself a finding about the gene and the disease. The quoted sentences say what the papers report.
pseudobulbar palsy (1 paper, 2021). A condition affecting cranial nerves IX-XII resulting from upper motor neuron damage arising from a variety of causes. "The other gene we found, the OR52L1 (Olfactory Receptor Family 52 Subfamily L Member 1), belongs to the same gene family and is associated with diseases such as Pseudobulbar Palsy." (PMID 34070492, 2021).
OR52L1 also shares sentences with these, for which no sentence is quoted: retinitis pigmentosa (1 paper).